HMGB1 (high mobility group box 1)
Diseases named in the same sentence as HMGB1 in open-access papers (continued):
Sharing a sentence is not in itself a finding about the gene and the disease.
gastric cancer (continued). "Similarly, HMGB1 in gastric cancer‐derived exosomes induces M2 macrophage polarization to promote tumor growth." (PMID 41354099, 2025). "Exosome transporter high-mobility group box 1 (HMGB1) derived from gastric cancer cells induces neutrophil autophagy via the HMGB1/Toll-like receptor 4 (TLR4)/nuclear factor-κB (NF-κB) signaling pathway, releasing pro-tumor cell migration factors, such as IL-1β and OSM." (PMID 38760815, 2024). "For example, its upregulation triggers apoptosis in gastric cancer cells by downregulating HMGB1." (PMID 39759512, 2024). "Indeed, high mobility group protein B1 (HMGB1) in gastric cancer (GC) cell-derived exosomes induced M2-like macrophage polarization and promoted GC progression." (PMID 38542388, 2024). "miR-129-5p is less expressed and HMGB1 is more expressed in gastric cancer than in normal tissues." (PMID 39759512, 2024). "In gastric cancer research, it was found that extracellular HMGB1 could be overexpressed as a cancer cell growth factor." (PMID 37897664, 2024). "Previous study has verified that HMGB1 was a target of miR-1179 in gastric cancer." (PMID 37516834, 2023). "Moreover, tumor-derived exosomes re-educated neutrophils to exhibit an immunosuppressive microenvironment to promote gastric cancer via high mobility group box-1 (HMGB1) activated STAT-3 expression and increase PD-L1 activity." (PMID 37108809, 2023). "In addition, PD-L1 on neutrophils is upregulated by gastric cancer cell-derived EVs, activated by HMGB1 via phosphorylating STAT3 and downstream molecules, which suppresses T-cell immunity to have a pro-tumor influence." (PMID 36405712, 2022). "We further searched the literature to understand the expression of HMGB1 in various tumours, and we found that HMGB1 was expressed at high levels in other tumours such as ovarian cancer and gastric cancer; overexpression of HMGB1 was related to the poor prognosis of various tumours." (PMID 35379200, 2022). "Data from our small cohort of gastric cancer patients show that HMGB1 levels were correlated with primary tumor progression and distant metastasis, whereas CML-HMGB1 levels were correlated with primary tumor progression, lymph node metastasis, distant metastasis, and stage." (PMID 34068442, 2021). "The role of CML-HMGB1 was compared to that of HMGB1 in the context of gastric cancer." (PMID 34068442, 2021). "Considering their findings, they have suggested that curcumin might be an anti-lymphangiogenesis agent in the treatment of gastric cancer by inhibiting HMGB1/VEGF-D signaling." (PMID 34456716, 2021). "Furthermore, gastric cancer cell-derived sEVs were enriched in high mobility group box-1 (HMGB1) and activated tumor-promoting neutrophils via the TLR4/NF-κB signaling pathway." (PMID 33791224, 2021). "In this study, we examined the CML modification of HMGB1 and its significance in gastric cancer." (PMID 34068442, 2021). "Cancer metastasis and drug resistance are both barriers to cancer treatment and HMGB1 might be a promised molecular target for both in gastric cancer." (PMID 31905926, 2019). "In addition, HMGB1 antagonist reversed gastric cancer tissue-derived exosomes-induced increases of ATG7 and BECN1 expression in neutrophils." (PMID 30292233, 2018). "In conclusion, we demonstrate in this study that gastric cancer cell-derived exosomes induce autophagy and pro-tumor activation in neutrophils through the HMGB1/TLR4/NF-кB signaling pathway, which finally promotes the proliferation and migration of gastric cancer cells." (PMID 30292233, 2018). "Finally, the promoting effect of supernatant from gastric cancer tissue-derived exosomes-treated neutrophils on gastric cancer cell migration was impaired by HMGB1 antagonist." (PMID 30292233, 2018). "We found that a higher level of HMGB1 in gastric cancer patients predicted poorer prognosis." (PMID 30292233, 2018). "Finally, HMGB1 knockdown blocked the promoting effect of GC-Ex-activated neutrophils on gastric cancer cell migration." (PMID 30292233, 2018).
gastric cancer (continued). "Moreover, gastric cancer tissue-derived exosomes-induced expression of inflammatory factors in neutrophils was inhibited by HMGB1 antagonist." (PMID 30292233, 2018). "Finally, the promoting effect of supernatant from GC-Ex-treated neutrophils on gastric cancer cell migration was impaired by HMGB1 antagonist." (PMID 30292233, 2018). "However, the opposite results were also obtained in some cancers—namely, high levels of HMGB1 were correlated with better prognosis in patients with esophageal cancer and gastric cancer." (PMID 28536706, 2017). "Contrarily, HMGB1-mediated autophagy may protect gastric cancer cells from the chemotherapeutic vinca alkaloid, vincristine." (PMID 25652880, 2015). "Therefore, HMGB1 induced cell proliferation in gastric cancer cells via activation of the MEK/ERK signaling pathway." (PMID 25652880, 2015). "Nearly all gastric adenocarcinomas show HMGB1-positive labeling, primarily in the nucleus and HMGB1 in gastric cancer cells may be significantly increased compared to that in the epithelial and stromal cells in normal tissues." (PMID 25652880, 2015). "Nevertheless, it is still unknown how vitexin inhibits HMGB1 in gastric cancer cells." (PMID 40725244, 2025). "In a study, proteomic analysis of gastric cancer (GC) cells revealed HMGB1 among the 1,014 proteins with a total of 2,375 lactylation sites." (PMID 40584966, 2025). "In addition, we evaluated the level of HMGB1 in normal gastric tissues and gastric cancer tissues." (PMID 38469295, 2024). "The present study investigated the roles of extracellular HMGB1 in the progression of gastric cancer (GC) and the therapeutic effects of recombinant human soluble thrombomodulin (rTM) targeting HMGB1." (PMID 35328684, 2022). "Therefore, it is suggested that CML-HMGB1 might be more significantly involved in gastric cancer progression than HMGB1." (PMID 34068442, 2021). "Furthermore, HMGB1 expression was upregulated in gastric cancer tissues." (PMID 30292233, 2018). "Although autophagy may regulate selective HMGB1 release in some tumor types, the mechanisms of its extracellular release from gastric cancer cells undergoing autophagy and activation of surface receptor-mediated intracellular signaling pathways are not well characterized." (PMID 25652880, 2015). "A recent mechanistic study showed that in gastric cancer, hypoxic tumor microenvironments stimulate NET formation via the HMGB1/TLR4/p38 MAPK pathway, and that elevated NET levels are associated with poorer prognosis." (PMID 41333516, 2025). "By engaging the receptor for advanced glycation end products (RAGE), HMGB1 enhances the protumorigenic polarization of M2-like macrophages, which in turn augments the invasive capacity of co-cultured MKN-45 gastric cancer cells." (PMID 41459539, 2025). "In gastric cancer, YAP–TEAD targets HMGB1, which also acts upstream of FAK; silencing HMGB1 reverses YAP‐driven FAK activation and cell proliferation." (PMID 40895190, 2025). "The same study revealed that inhibiting HMGB1 down-regulated Bcl-2 and MMP-2 but up-regulated Bax in gastric cancer cells." (PMID 40264171, 2025). "GC-Ex activates neutrophils through the HMGB1/TLR4/NF-κB signaling pathway, thereby promoting tumor metastasis in gastric cancer." (PMID 40564191, 2025). "Moreover, by investigating the function of HMGB1 in facilitating the development of gastric cancer, our results indicate that HMGB1 could potentially emerge as an innovative and appealing target for prospective clinical interventions aimed at treating gastric cancer." (PMID 38469295, 2024). "In gastric cancer cells, RAGE expression induced by HMGB1 fosters cell proliferation and migration through ERK signaling activation." (PMID 38250151, 2024). "Gefitinib is an EGFR inhibitor, and HMGB1 release from tumor cells treated with gefitinib promotes autophagy, interacts with RAGE, and induces ERK1/2 signaling in gastric cancer cells." (PMID 36613714, 2022).
gastric cancer (continued). "Various studies report on the overexpression and increased release of HMGB1 in cancer, e.g., in non-small-cell lung carcinoma (NSCLC), breast cancer, gastric cancer, hepatocellular carcinoma, pancreatic carcinoma, colorectal carcinoma and lymphoma." (PMID 33672622, 2021). "Here, we found that PAFAH1B3 knockdown in gastric cancer cells downregulated the levels of IRS1, Myc, HMGB1, and PTGS2, which were reported to serve as oncogenes in many types of cancers." (PMID 33732641, 2021). "Since it was considered that CDDP sensitivity can be promoted by inhibiting HMGB1, we examined the effect of EP and TAN in two types of human gastric cancer cell lines, TMK−1 and MNK74." (PMID 31905926, 2019). "Here, we examined the expression of four metastasis-related genes (namely, c-met, HMGB1, RegIV, PCDHB9) in 39 cases of gastric cancer treated with neoadjuvant therapy with CDDP or CDDP+5-fluorouracil and evaluated its association with CDDP responsiveness." (PMID 31905926, 2019). "Treatment of TMK-1 and MKN74 human gastric cancer cell lines with ethyl pyruvate (EP) or tanshinone IIA (TAN), which are reported to inhibit HMGB1 signaling, showed a 4–5-fold increase in inhibition by CDDP." (PMID 31905926, 2019). "Gastric cancer cell-derived exosomes carried high mobility group box-1 (HMGB1) that interacted with toll-like receptor 4 (TLR4) to activate NF-κB and induce autophagy in neutrophils, which in turn promoted gastric cancer cell migration." (PMID 30292233, 2018). "HMGB1-induced EMT has been identified in colorectal and gastric cancers, and is activated by the RAGE/NF-κB pathways." (PMID 29283384, 2017). "Most importantly, it has been proven that overexpressed HMGB1 enhances IL-8 secretion in tumor cells and over-secreted IL-8 promotes EMT activation in gastric cancer cells." (PMID 27667993, 2016). "HMGB1 was found to up-regulate the expression of MMP-9, which belongs to matrix metalloproteinases (MMPs) involved in the initiation, invasion, and metastasis of many kinds of cancers, in glioma and gastric cancer cells, which may explain its association with invasion and metastasis of glioma tumor." (PMID 25772485, 2015). "In contrast, miR-181b inhibits cell growth in gastric cancer by targeting CREB127 and increases drug sensitivity in acute myeloid leukemia via targeting HMGB1 and Mcl-128." (PMID 26620926, 2015). "Extracellular HMGB1 interacted with RAGE and activated ERK signaling responsible for gastric cancer cell proliferation." (PMID 25652880, 2015). "Gastric carcinoma cell lines (BGC-823, SGC-7901, MKN-28 and MKN-45) exhibited high HMGB1 levels in both the nuclei and cytoplasm, whereas gastric epithelial cells showed a reduced HMGB1 level, primarily localized to the nucleus." (PMID 25652880, 2015). "Although many studies have indicated that high-mobility group box 1 protein (HMGB1) is associated with oncogenesis and a worse prognosis, the prognostic value of HMGB1 in gastric cancer (GC) remains unclear." (PMID 23866030, 2013). "Silencing of HMGB1 expression by an HMGB1-specific RNAi lentiviral vector has been shown to reduce matrix metalloproteinase 9 (MMP9) expression and metastatic capacity in MGC-803 gastric carcinoma cells." (PMID 23378947, 2013). "Notably, the high expression of HMGB1 along with that of its receptor, i.e., receptor for advanced glycation end products (RAGE), correlates well with the progression of gastric cancer." (PMID 34068442, 2021). "The correlation between HMGB1 and CD68 has been observed in gastric cancer, but the correlation between HMGB1 and CD163 and CD33 has not been reported." (PMID 34257571, 2021). "Treatment of gastric cancer cells with CML-HMGB1 enhanced cell proliferation and invasion, sphere formation, and protection from thapsigargin-induced apoptosis, and decreased 5-FU sensitivity in comparison to HMGB1." (PMID 34068442, 2021).
gastric cancer (continued). "Regarding the gastric cancer cell-derived exosomes, they could regulate pro-tumor activation (polarization) of neutrophils via autophagy as well as HMGB1/TLR4/NF-κB signaling pathway induction which promoted proliferation and migration of gastric cancer cells." (PMID 32765827, 2020). "They found that HMGB1 was transported by GC-derived exosomes to activate NF-κB pathway through interaction with TLR4, resulting in an increased autophagic response in neutrophils and in turn, promoting gastric cancer cell migration." (PMID 30876419, 2019). "In a study performed by Zhang, the expression of HMGB1 protein in four gastric cancer cell lines and non-malignant GES-1 cells was assessed by western blot analysis and immunofluorescence." (PMID 30245980, 2018). "In silico gene expression analysis (Dataset GSE13911 retrieved from Gene Expression Omnibus) showed remarkably increased HMGB1 expression in gastric cancer tissues compared to the paired non-cancerous tissues." (PMID 30292233, 2018). "HMGB1 and RAGE are significantly expressed in gastric adenocarcinoma, and EP treatment (40 mg/kg and 80 mg/kg intraperitoneally injected once a day for 2 weeks) inhibits gastric cancer growth via regulation of the HMGB1-RAGE and Akt pathways." (PMID 27980458, 2016). "We first examined the amount of HMGB1 in 8 gastric cancer tissue samples and corresponding non-tumor gastric tissues by immunoblotting analysis." (PMID 25652880, 2015). "We observed that the HMGB1 expression in gastric cancer tissues was increased compared to the non-cancerous tissues, while the serum HMGB1 levels in cancer patients were higher than that in the healthy volunteers." (PMID 25652880, 2015). "Gastric cancer cell‐derived exosomes induce autophagy and protumor activation through the HMGB1/TLR4/NF‐кB signaling pathway to enhance the growth and migration of GC cells." (PMID 38685971, 2024). "However, the TLR-mediated tumor-promoting effects of HMGB1 in gastric cancer have been negative, and the HMB1-RAGE-signaling pathway has been reported as the main tumor-promoting factor." (PMID 35328684, 2022). "In gastric cancer treated with 5-fluorouracil (5-FU), transformation of M2-type TAMs was ascribed to accumulation of reactive oxygen species (ROS), activating hypoxia-inducible factor 1α (HIF-1α) signaling, driving the expression of high-mobility group box 1(HMGB1)." (PMID 34095111, 2021). "In addition, we found that HMGB1 expression levels were higher in exosomes from the culture supernatants of gastric cancer tissues than non-cancerous tissues and in exosomes from the serum samples of gastric cancer patients than healthy controls." (PMID 30292233, 2018). "The expression of HMGB1 was increased in gastric cancer tissues compared to non-cancerous tissues." (PMID 30292233, 2018). "Similarly, in a previous study, the HMGB1 expression in gastric cancer tissues was increased as compared to that in non-cancerous tissues." (PMID 27667993, 2016). "Therefore, we measured HMGB1 in paired gastric cancer tissues and non-cancerous tissues by ELISA." (PMID 30292233, 2018). "Western blot analysis and immunofluorescence were performed in four gastric cancer cell lines and non-malignant GES-1 cells and showed that HMGB1 protein expression was much higher in the cancer cells compared to the level in the GES-1 cells." (PMID 25652880, 2015).
glioma (117 papers, 2012 to 2025). A benign or malignant brain and spinal cord tumor that arises from glial cells (astrocytes, oligodendrocytes, ependymal cells). "HMGB1—a chromatin-binding protein—attracts various immune cells and plays a crucial role in anti-tumor immunity; notably, HMGB1 can induce M1-like polarization of tumor-associated macrophages (TAMs) and enhance glioma cell sensitivity to temozolomide." (PMID 40297580, 2025). "HMGB1 is often overexpressed in glioma, and its interaction with RAGE on tumor-associated microglia can promote an immune-suppressive, tumor-promoting microenvironment." (PMID 41226481, 2025). "In fact, HMGB1, released from necrotic glioma cells, has been implicated in glioma formation, invasion and progression through mitogen-activated protein kinase/extracellular signal-regulated kinase pathway activation." (PMID 36652782, 2023). "HMGB1 has been shown to be highly expressed in human glioma cells and to be associated with poor prognosis." (PMID 38003396, 2023). "In the glioma microenvironment, various endogenous TLRs ligands, such as heat shock proteins, high-mobility-group box 1 (HMBG1), and damage-associated molecular patterns (DAMPs), are upregulated by necrotic cells." (PMID 35711434, 2022). "HMGB1 is believed to be a pivotal factor in the association between necrosis and malignancy in glioma due to its role as an autocrine factor, which can promote the growth and migration of tumor cells." (PMID 25574225, 2015). "When all gliomas were considered, increasing levels of HMGB1 expression were clearly associated with decreased survival time." (PMID 25574225, 2015). "HMGB1 expression levels had a significant association with decreased survival time for patients with glioma." (PMID 25574225, 2015). "Previous studies have found an increased expression of HMGB1 in human glioma tissues; however, the associations between expression levels, pathology grades and the prognostic significance are rarely reported." (PMID 25574225, 2015). "High-mobility group box 1 (HMGB1), a key component associated with neutrophil extracellular traps (NETs), interacts with RAGEs on tumor cells, triggering NF-κB signaling activation in glioma cells." (PMID 40282474, 2025). "Whether and how HMGB1 is implicated in the malignant progression of glioma tumors need to be validated using a larger cohort of glioma patient samples and animal models." (PMID 37575469, 2023). "Previous studies have indicated that HMGB1 is implicated in regulating the progression of glioma." (PMID 37575469, 2023). "Finally, it is noteworthy that glioma cells exhibited an increase in stemness markers upon exposure to HMGB1, a type of damage-associated molecular pattern (DAMP) that triggers TLR signaling." (PMID 37880659, 2023). "HMGB1 has also been implicated as a key mediator of glioma resistance to TMZ." (PMID 34975408, 2021). "Moreover, rescue assays reveal that HMGB1 overexpression (or miR-107 inhibition) reverses the glioma growth inhibition caused by LINC00662 knockdown." (PMID 32913464, 2020). "This suggests that HMGB1 expression at the highest levels is associated with a more extreme malignant phenotype of glioma and may also be associated with increased treatment resistance." (PMID 25574225, 2015). "Recent studies have demonstrated that lactate stimulates macrophage M2 polarization and secretes HMGB1, thereby promoting glioma cell invasion." (PMID 40148311, 2025). "Glucose influences the HMGB1 signaling pathway through SIRT1, where low SIRT1 levels due to high glucose result in the activation of HMGB1, promoting the proliferation, migration, and invasion of glioma cells while inhibiting apoptosis." (PMID 40710366, 2025). "In malignant brain tumors derived from glial cells (glioma), the HMGB1/RAGE axis is of particular interest, as it co-opts inflammatory pathways." (PMID 41226481, 2025).